PGR (progesterone receptor)
Diseases named in the same sentence as PGR in open-access papers (continued):
Sharing a sentence is not in itself a finding about the gene and the disease.
triple-negative breast carcinoma (continued). "Clinically, this heterogeneous disease is classified into three main types based on estrogen receptor (ER), progesterone receptor (PR), and human epidermal growth factor receptor 2 (HER2) status: hormone receptor (HR)-positive, HER2-positive, and triple-negative breast cancers (TNBC)." (PMID 38630392, 2024). "Breast cancer classification, based on hormone receptor expression, delineates four subtypes: Oestrogen Receptor-Positive (ER+), Progesterone Receptor-Positive (PR+), Human Epidermal Growth Factor Receptor 2-Positive (HER2+), and the notably aggressive triple-negative breast cancer (TNBC)." (PMID 39619199, 2024). "All patients’ tissue biopsy samples were examined to check the expressions of the estrogen receptor, progesterone receptor, human epidermal growth factor receptor 2 (HER2), and the Ki67 (MKI67) value, and two patients belonged to the triple-negative breast cancer (TNBC) group." (PMID 39330049, 2024). "Based on the expression status of Human Epidermal Growth Factor Receptor 2 (HER2), Estrogen Receptor (ER), and Progesterone Receptor (PR), breast cancer can be classified into four molecular subtypes: Luminal A, Luminal B, HER2-positive, and triple-negative breast cancer." (PMID 39109338, 2024). "It is mainly classified into 3 main types by the presence of human epidermal growth factor 2, estrogen or progesterone receptor, and triple-negative breast cancer, lacking all 3 standard molecular markers." (PMID 39319107, 2024). "Triple-negative breast cancer (TNBC) accounts for 15%–25% of all breast cancers as it lacks oestrogen receptor (ER), progesterone receptor (PR), and human epidermal growth factor receptor 2 (HER2) expression, and exhibits high genomic instability with a high mutation burden." (PMID 38481526, 2024). "Triple-negative breast cancers (TNBCs) are defined as their negative expression for the estrogen receptor (ER), progesterone receptor (PR) and human epidermal growth factor receptor 2 (HER2)." (PMID 39741338, 2024). "Based on the expression levels of estrogen receptor (ER), progesterone receptor (PR), and human epidermal growth factor receptor 2 (HER2), breast cancer is classified into three molecular subgroups, ER+, HER2+, and triple-negative breast cancer (TNBC)." (PMID 39906392, 2024). "MDA-MB-231 is representative of the highly aggressive triple-negative breast cancer (TNBC), and MCF7A represents the adherent derivation of a relatively less aggressive luminal type A cancer with estrogen receptor (ER)-positive and progesterone receptor (PR)-positive characteristics." (PMID 38473331, 2024). "Triple-negative breast cancer (TNBC) accounts for 10 to 20% of newly diagnosed invasive breast cancers and is defined by the absence of immunostaining for estrogen receptor (ER), progesterone receptor (PgR) and human epidermal growth factor receptor-2 (HER2)." (PMID 37296893, 2023). "Breast MEC is extremely rare and estrogen receptor, progesterone receptor, and human epidermal growth factor receptor-2 negative breast cancer with a good prognosis, which is different from other highly malignant triple-negative breast cancers." (PMID 37144989, 2023). "Triple-negative breast cancer (TNBC) is an aggressive type of breast cancer characterized by the absence of expression of progesterone receptor (PR), estrogen receptor (ER), and epidermal growth factor receptor-2 (HER2)." (PMID 36968199, 2023). "Triple-negative breast cancer (TNBC) represents 15–20% of breast cancer cases and is associated with a lack of estrogen receptor (ER), progesterone receptor (PR), and human epidermal growth factor receptor-2 (HER2) expression." (PMID 36836424, 2023). "Triple-negative breast cancer (TNBC) is characterized by a negative expression of the progesterone receptor (PR), the estrogen receptor (ER), and human epidermal growth factor receptor 2 (HER2)." (PMID 36674773, 2023).
triple-negative breast carcinoma (continued). "These categories comprise ER-positive, ER-negative/HER2-positive, and ER-negative/HER2-negative cases (primarily PgR-negative, also known as triple-negative breast cancer)." (PMID 37627192, 2023). "Triple-negative breast cancer (TNBCs) is an aggressive subtype that is characterized by a lack of estrogen receptor (ER), progesterone receptor (PR), and Her2 receptor levels." (PMID 36777188, 2023). "The cell line MCF-7 is human breast adenocarcinoma expressing estrogen receptor alpha (ER-α), while the cell line MDA-MB-231 represents triple negative breast cancer (TNBC) adenocarcinoma and lacks ER, progesterone receptor (PR), and human epidermal growth factor receptor 2 (HER2)." (PMID 37108514, 2023). "Triple Negative Breast Cancer (TNBC) as the most aggressive form of BC is characterized by a lack of estrogen receptor (ER), epidermal growth factor receptor 2 (HER-2), and progesterone receptor (PR) that results in the failure of targeted therapies in these patients." (PMID 37596669, 2023). "In another study involving patients with triple-negative breast cancer (TNBC), which lacks expression of ER, PgR, and HER2, a higher incidence of lung cancer and lower overall survival rates were observed compared to patients with ER and PgR positivity." (PMID 37509283, 2023). "Breast cancer can be classified into four phenotypes including luminal A, luminal B, HER2-positive, and triple-negative breast cancer (TNBC), according to the molecular expression of estrogen receptor (ER), progesterone receptor (PR), and human epidermal growth factor receptor 2 (HER2)." (PMID 37185776, 2023). "Triple-negative breast cancer is characterized by a lack of expression of progesterone receptor (PR), estrogen receptor (ER) and HER2, and has poor prognosis." (PMID 35517864, 2022). "Triple negative breast cancers (TNBCs) are a relatively heterogeneous breast cancer subtype, broadly characterised by the absence of the oestrogen receptor (ER), progesterone receptor (PR) and HER2 (ERBB2), found in other subtypes of the disease." (PMID 35768547, 2022). "Truncating mutations were present in 28% of the cohort and were associated with age, grade, tumour size, oestrogen receptor (ER), progesterone receptor (PR), human epidermal growth factor receptor 2 (HER2) and triple-negative breast cancer (TNBC) classification." (PMID 35743117, 2022). "Triple-negative breast cancers (TNBCs) that do not express the genes for estrogen receptor (ER), progesterone receptor (PR) or Her2, lack known targetable biomarkers with an overall poor prognosis." (PMID 35593465, 2022). "MDA-MB-231 is a highly aggressive, invasive, and poorly differentiated triple-negative breast cancer cell line, lacking ER and progesterone receptor expression as well as HER2 amplification." (PMID 36077298, 2022). "Triple negative breast cancer (TNBC), i.e., ER (estrogen receptor)-, PR (progesterone receptor)-, and HER-2 (human epithelial growth factor receptor-2)-, accounting for 15−20% in breast cancer, is a highly aggressive subtype with a significantly inferior prognosis than non-TNBC1." (PMID 34934050, 2021). "Triple-negative breast cancer (TNBC) is characterized by the absence of estrogen receptor-α progesterone receptor and human epidermal growth factor receptor-2." (PMID 34959717, 2021). "Triple negative breast cancer is defined by lack of expression of all three receptors generally found in breast cancer subtypes: the estrogen receptor (ER), progesterone receptor (PR) and human epidermal growth factor receptor 2 (HER2)." (PMID 34440076, 2021). "Based on cell surface hormone receptors, breast cancer can be divided into 4 subtypes: Luminal A-estrogen receptor positive (ER+), Luminal B-progesterone receptor positive (PR+), human epidermal growth factor receptor 2 positive (HER2+), and triple-negative breast cancer (TNBC)." (PMID 33929971, 2021).
triple-negative breast carcinoma (continued). "Triple-negative breast cancer (TNBC) is characterized by a lack of progesterone receptor (PR), estrogen receptor (ER), and human epidermal growth factor receptor-2 (HER-2) expression." (PMID 34502165, 2021). "Triple-negative breast cancers (TNBCs) represent 10–20% of all breast cancers and are characterized by negative or low estrogen receptor (ER), progesterone receptor (PR), and human epidermal growth factor receptor 2 (HER2) expression." (PMID 33649296, 2021). "Triple-negative breast cancers (TNBCs) are defined by the lack of expression of estrogen receptor (ER), progesterone receptor (PR), and human epidermal growth factor receptor 2 (HER2/neu)." (PMID 34188985, 2021). "Basal-like and claudin-low tumors form the majority of triple-negative breast cancers (TNBCs), an aggressive subgroup of breast malignancies defined as tumors lacking expression of the estrogen receptor (ER), progesterone receptor (PR), and HER2." (PMID 32647202, 2020). "The majority of basal-like breast cancers are defined triple-negative breast cancers (TNBC), as they lack the expression of the estrogen receptor (ER), progesterone receptor (PR) and human epidermal growth factor receptor 2 (HER2/neu), making them difficult to treat." (PMID 31311575, 2019). "Unlike the other breast cancer subtypes, triple negative breast cancer is negative for ER (Estrogen Receptor), PR (Progesterone Receptor), and HER-2 (human epidermal growth factor receptor 2) receptors." (PMID 31394796, 2019). "Triple-negative breast cancers (TNBCs) are breast cancers that do not express three receptor genes: estrogen receptor (ER), progesterone receptor (PR), and human epidermal growth factor receptor (HER)-2 genes." (PMID 31921620, 2019). "In Triple-Negative Breast Cancers (TNBCs), estrogen receptor (ER), progesterone receptor (PR) and HER2/neu genes are not expressed." (PMID 31754359, 2019). "The most aggressive, triple-negative breast cancer (TNBC), lacks expression of valid predictive markers [oestrogen receptor (ER), progesterone receptor (PR) and epidermal growth factor receptor 2 (HER2)], and thus devoid of clear therapeutic targets, it presents a serious clinical challenge." (PMID 29923083, 2018). "Triple-negative breast cancer is characterized by the lack of expression of estrogen receptors (ER), progesterone receptors (PgR), and the HER-2 gene." (PMID 30524958, 2018). "Triple-negative breast cancer (TNBC), in which the estrogen receptor (ER), progesterone receptor (PR), and human epidermal growth factor receptor 2 (HER2) are not expressed, accounts for approximately 170,000 of the 1 million breast cancer cases which are diagnosed worldwide annually." (PMID 29666962, 2018). "Triple negative breast cancers (TNBCs) do not respond to conventional estrogen receptor/progesterone receptor/human epidermal growth factor receptor-2 targeted interventions due to the absence of the respective receptor targets." (PMID 30563138, 2018). "Triple-negative breast cancers (TNBC) are defined as lack of expression of progesterone receptor (PR) and oestrogen receptor (ER) and amplification of human epidermal growth factor receptor 2 (HER2) gene." (PMID 28402944, 2017). "Previous research identified ETS-1 as a novel therapeutic target of triple negative breast cancer (TNBC), which does not express ER, progesterone receptor (PR), or HER2 and is associated with a significant risk of poor prognosis and metastasis." (PMID 29312607, 2017). "Triple-negative breast cancer is defined by the lack of expression of estrogen receptor (ER), progesterone receptor (PR), and human epidermal growth factor receptor 2 (Her2), but it is genetically and genomically diverse." (PMID 27663795, 2016).
triple-negative breast carcinoma (continued). "Estrogen receptor-, progesterone receptor- and HER2-negative breast cancers, also known as triple-negative breast cancers (TNBCs), have poor prognoses and are refractory to current therapeutic agents, including epidermal growth factor receptor (EGFR) inhibitors." (PMID 27462789, 2016). "Triple negative breast cancer is a heterogeneous disease defined by negative expression for estrogen receptor (ER) and progesterone receptor (PR), and normal (low) expression levels of Her2." (PMID 27049755, 2016). "Within the molecular subtypes, basal-like or triple-negative breast cancers (TNBC), which lack expression of estrogen receptor (ER), progesterone receptor (PR) and HER2/neu tyrosine kinase receptor, are generally associated with the worst prognosis due to its high resistance to chemotherapy." (PMID 26059540, 2015). "Triple-negative breast cancers (TNBCs) refer to describe those cancers which do not express oestrogen receptor (ER), progesterone receptor (PR) or overexpress human epidermal growth factor receptor 2 (Her2/neu)." (PMID 26196284, 2015). "However, 15–20% of breast tumors lack ERα, HER2 and a clinically relevant biomarker of ERα signaling, progesterone receptor (PGR); this subtype is termed triple-negative breast cancer (TNBC)." (PMID 26554309, 2015). "Triple negative breast cancer is defined by lack of expression of estrogen receptor (ER), progesterone receptor (PR) and human epidermal growth factor receptor (HER2)." (PMID 26312204, 2015). "For triple negative breast cancer, which is characterized by the absence of expression of estrogen receptor (ER), progesterone receptor (PR) and human epidermal growth factor receptor 2 (HER2), it is currently the only available systemic treatment option." (PMID 26433948, 2015). "Over the past decade, the term triple-negative breast cancer (TNBC) has been used to classify tumors that lack detectable expression of the estrogen receptor (ER) and progesterone receptor (PR) and amplification of human epithelial growth factor receptor 2 (HER2)." (PMID 25103565, 2014). "Further, hormone receptors are weak predictors of patient outcome; only the combined absence of ERα, PgR and HER-2/neu associates with aggressive triple-negative breast cancers." (PMID 24824621, 2014). "Triple-negative breast cancers (TNBCs) account for about 15% of all invasive breast cancers and are defined as tumors that lack expression of estrogen receptor (ER) and progesterone receptor (PR), and do not show overexpression of HER2/neu." (PMID 23110154, 2012). "Triple-negative breast cancer is a recent term and refers to cancers that do not express ER, PgR and HER2 receptors." (PMID 19591668, 2009). "Based on molecular markers, including estrogen receptor (ER), progesterone receptor (PR) and human epidermal growth factor receptor 2 (HER2), breast cancer can be divided into three subtypes: hormone receptor (HR) positive, HER2 positive and triple-negative breast cancer (TNBC)." (PMID 40303918, 2025). "Triple-negative breast cancer (TNBC) comprises a heterogeneous disease group defined by lack of estrogen receptor (ER), progesterone receptor (PR), and HER2 expression and is often associated with increased genomic instability, high mitotic rates and poor prognosis." (PMID 38772416, 2024). "Triple-negative breast cancer (TNBC) is associated with poor prognosis and limited treatment options due to the lack of important receptors (estrogen receptor [ER], progesterone receptor [PR], and human epidermal growth factor receptor 2 [HER2]) used for targeted therapy." (PMID 38286854, 2024). "Triple-negative breast cancer(TNBC) is a subtype of breast cancer, which accounts for approximately 15–25% of breast cancer cases and is characterized by the absence or reduction of estrogen receptor (ER), progesterone receptor (PR), and human epidermal growth factor receptor 2 (HER-2)." (PMID 37773118, 2023).
triple-negative breast carcinoma (continued). "Triple-negative breast cancers (TNBCs, lacking the expression of estrogen receptor (ER), progesterone receptor (PR), and human epidermal growth factor-2 (HER2)) can benefit from this metabolic switch and, consistently, can be targeted by novel therapeutic compounds called glycolysis inhibitors." (PMID 37895048, 2023). "MBC commonly shows a triple negative breast cancer phenotype, due to the lack of expression of the estrogen receptor (ER), progesterone receptor (PR), and human epidermal growth factor receptor-2 (HER2), and is managed with surgical resection in combination with radiotherapy and chemotherapy." (PMID 34247567, 2022). "On the basis of the expression of hormone receptors estrogen receptor (ER), progesterone receptor (PR), and human epidermal growth factor receptor 2 (HER2), breast cancer is clinically categorized into three primary subtypes: luminal, HER2-positive, and triple-negative breast cancer (TNBC)." (PMID 36355532, 2022). "Depend on molecular and histological evidences, BC could be classified into BC expressing hormone receptor (estrogen receptor (ER+) or progesterone receptor (PR+)), BC expressing human epidermal receptor 2 (HER2+) and triple-negative breast cancer (TNBC) (ER−, PR−, HER2−)." (PMID 34123778, 2021). "In triple-negative breast cancers (TBNCs), which are very aggressive tumors characterized by the lack of ER, progesterone receptor (PR), and HER2, high expression and reciprocal compensation between β1 integrin and EGFR signaling synergize to support tumor progression and metastasis." (PMID 34131655, 2021). "The term triple-negative breast cancers (TNBC) was first used in 20051 to describe a subset of tumours characterised by absence or low levels of expression of oestrogen receptor (ER), progesterone receptor (PgR), and human epidermal growth factor receptor 2 (HER2)." (PMID 31792349, 2020). "Moreover, breast cancer is considered hormone-receptor-positive when it possesses estrogen receptor (ER) and/or progesterone receptor (PR), whereas a tumor is considered as triple negative breast cancer when lacking in ER, PR and HER2 expression." (PMID 33027908, 2020). "We used MDA-MB-231 breast cancer cells in this study as a representative model of a basal-like, triple negative breast cancer subtype, negative for estrogen receptor (ER), progesterone receptor (PR), human epidural growth factor receptor 2 (HER2), and E-cadherin expression." (PMID 31717800, 2019). "In particular, the triple negative breast cancer, lacking of the estrogen receptor (ER), progesterone receptor (PR) and human epidermal growth factor receptor 2 (HER2), is resistant to therapies, and is associated with reduced survival for tumor recurrence and metastasis." (PMID 31731707, 2019). "Triple-negative breast cancers (TNBCs), classified as estrogen receptor (ER)-negative, progesterone receptor (PR)-negative and lacking human epidermal growth factor receptor 2 (HER2) amplification remain the most aggressive breast tumor subtype, and approximately 50% of TNBCs classify as basal-like." (PMID 30458886, 2018). "Triple-negative breast cancer (TNBC), is a specific subtype of epithelial breast tumors that are immuno-histochemically negative for the protein expression of the estrogen receptor (ER), the progesterone receptor (PR) and lack over expression/gene amplification of HER2." (PMID 27199756, 2016). "Interestingly, triple negative breast cancers, which do not express oestrogen receptor, progesterone receptor and the tyrosine kinase receptor HER2, were found to be positive for sortilin in 59% of cases." (PMID 25871389, 2015). "Triple Negative Breast Cancer, TNBC, a highly aggressive and metastatic type of breast cancer, is characterized by loss of expression of the estrogen receptor (ER), progesterone receptor (PR), and a lack of overexpression of the human epidermal growth factor receptor 2 (HER2)." (PMID 24244833, 2013).